OGFOD3 (2-oxoglutarate and iron dependent oxygenase domain containing 3)
Synonyms: C17orf101; FLJ22222
Tractability: Antibody: UniProt predicts a signal peptide or a membrane-spanning region. PROTAC: ubiquitination databases record sites on it; its protein half-life has been measured.
Gene: Protein-coding gene on chromosome 17 (82,389,210 to 82,418,637, reverse strand). Ensembl gene ENSG00000181396.
Subcellular location: Membrane
Subcellular location (Human Protein Atlas): Nucleoplasm
Gene Ontology:
Molecular function: iron ion binding; L-ascorbic acid binding; oxidoreductase activity, acting on paired donors, with incorporation or reduction of molecular oxygen
Cellular component: membrane
Genetic constraint (gnomAD): Loss-of-function variants: 35 observed, 38.12 expected, observed/expected ratio (o/e) 0.92, 90% interval 0.7 to 1.22. The upper end of that interval is the gene's LOEUF score, 1.22, which puts it in group 5 of 6, group 1 being the genes least tolerant of losing a copy. Missense variants: 438 observed, 449.42 expected, observed/expected ratio (o/e) 0.97, 90% interval 0.9 to 1.05. Synonymous variants: 200 observed, 189.07 expected, observed/expected ratio (o/e) 1.06, 90% interval 0.94 to 1.19.
Homologues: Orthologues: macaque OGFOD3 (96% identical), chimpanzee OGFOD3 (87% identical), dog OGFOD3 (85% identical), mouse Ogfod3 (84% identical), pig OGFOD3 (84% identical), guinea pig OGFOD3 (83% identical), rat Ogfod3 (73% identical), tropical clawed frog ogfod3 (63% identical), zebrafish ogfod3 (55% identical).
Diseases named in the same sentence as OGFOD3 in open-access papers:
OGFOD3 is named in the same sentence as 5 diseases in open-access papers, as found by Europe PMC text mining. Sharing a sentence is not in itself a finding about the gene and the disease. The quoted sentences say what the papers report.
dyslipidemia (1 paper, 2017). "The variant rs62079523 in OGFOD3, associated with dyslipidemia in the dominant model, was found highly significant in the logistic regression model (p=0.005)." (PMID 29126409, 2017). "The common variant rs62079523 in OGFOD3 was found associated with dyslipidemia in the dominant model." (PMID 29126409, 2017). "Common variants in OGFOD3 and APOB as well as rare and common BAD variants were significantly (p<0.05) associated with dyslipidemia." (PMID 29126409, 2017).
Sepsis (1 paper, 2025). Sepsis is defined as life-threatening organ dysfunction caused by a dysregulated host response to infection. "Also, a uniform pattern of downregulation of gene OGFOD3 increases the risk of sepsis." (PMID 40665987, 2025). "While literature links NONO, FCAR, BMP6, RNF4, and RNASE2 to sepsis or Systemic Inflammatory Response Syndrome (SIRS), their interactions and the roles of PLEKHO1, OGFOD3, and CKAP4 in sepsis are less documented." (PMID 40665987, 2025).
OGFOD3 also shares sentences with these, for which no sentence is quoted: Insulin resistance (1 paper); Obesity (1); systemic inflammatory response syndrome (1).